TNF (tumor necrosis factor)
Diseases named in the same sentence as TNF in open-access papers (continued):
Sharing a sentence is not in itself a finding about the gene and the disease.
inflammation (continued). "The intestinal inflammation is characterized by a Th1 and Th17-mediated responses with enhanced expression of TNF-α, IFN-γ, IL-1β, IL-12, IL-6, IL-10 and IL-1761." (PMID 29872077, 2018). "Most pro-inflammatory cytokines (e.g. IFN-γ, TNF-α, and IL-1β) could reduce key TJ-associated proteins such as intracytoplasmic proteins (ZO-1, ZO-2) and transmembrane proteins (occluding and claudin), resulting in disruption of intestinal TJ barrier and the development of intestinal inflammation." (PMID 29538417, 2018). "Previous reports pointed out that over-expression of TNF-α and IFN-α induced by influenza virus is a cause of lung inflammation and can in turn result in tissue injury." (PMID 29739459, 2018). "Our lab has demonstrated that PPAR-β/δ signaling is involved in several pathological steps of DR, including TNFα-induced retinal vascular inflammation, VEGF-induced vascular permeability, and retinal angiogenesis." (PMID 29626212, 2018). "And this leads to a decline of proinflammatory cytokines, including TNF-a, IL-8 and IL-6, and in turn reduces the incidence of postoperative hepatic inflammation." (PMID 30006616, 2018). "IL-12p40 is one of the pro-inflammatory cytokines that was elevated in the dnTGF-βRII mice and depletion of IL-12p40 significantly ameliorated liver inflammation accompanied with a reduction of the Th1 cytokine, TNF-α." (PMID 30450101, 2018). "For example, genistein at physiological concentrations (0.1 μM-5 μM) inhibits tumor necrosis factor α (TNF-α)-induced endothelial inflammatory response and vascular inflammation in C57BL/6 mice via mediating the protein kinase pathway A." (PMID 28977871, 2017). "The involvement of MMPs in CS-induced lung inflammation can be mediated by the release of TNF-α from macrophages with the subsequent neutrophil influx." (PMID 28891938, 2017). "Taken together, these data reveal that both BMP9 and BMP10 synergize with TNFα to up-regulate endothelial-expressed molecules involved in leukocyte recruitment, in addition to BMP2, a factor previously implicated in endothelial inflammation." (PMID 28646109, 2017). "The fusion protein TAT-HSA-α-MSH inhibits NF-κB activation in human and TNFα production in mice to prevent brain inflammation in central nervous system (CNS) disorders." (PMID 28514752, 2017). "Using an established murine model of DEP-induced lung inflammation, we showed a role for TNF-α signaling in pulmonary inflammation upon DEP exposure." (PMID 28912506, 2017). "AngII infusion resulted in renal inflammation, highlighted by increased interleukin-6 and tumor necrosis factor-α concentrations, which were abolished by the αAnalogue." (PMID 28446517, 2017). "DT-13(25(R,S)-ruscogenin-1-O-[β-d-glucopyranosyl-(1→2)][β-d-xylopyranosyl-(1→3)]-β-d-fucopyranoside) has been identified as an important factor in TNF-α-induced vascular inflammation." (PMID 28855900, 2017). "In the present study, both CSE and CS were able to decrease the LPS-induced hepatic inflammation in the mice via downregulation of TNF-α, IL-1β, COX-2, and iNOS." (PMID 28617322, 2017). "Inhalation of aerosolized TNFα can also induce bronchial hyperresponsiveness accompanied by airway inflammation in healthy human subjects, but the underlying mechanism is not fully understood." (PMID 28659824, 2017). "Macrophage infiltration into WAT, which is accompanied by IL-6 and TNF-α production, is an early contributing event for the development of chronic low-grade systemic inflammation." (PMID 26871288, 2016). "The Th17-produced cytokine IL-17 is known to show strong synergy with TNF and these data therefore support the approach of combined cytokine blockade for therapy of refractory RA joint inflammation." (PMID 28004828, 2016). "Intestinal inflammation in colitic controls was characterized by a marked increase in pro- and anti-inflammatory cytokines TNF-α, IFN-γ, IL-1β, IL-6, IL-12, and IL-10, compared to normal controls." (PMID 27293323, 2016).
inflammation (continued). "Treatment of TNF-Tg mice with ferulic acid reduced synovial inflammation as well as cartilage and bone erosion, and it also restored lymphatic contraction and drainage." (PMID 26970913, 2016). "Acute brain inflammation after ischemia-reperfusion, as estimated by expression levels of pro-inflammatory cytokines such as interleukin (IL)-1β and tumor necrosis factor alpha (TNF)-α, was significantly suppressed in Angptl2 KO compared to control mice." (PMID 27861531, 2016). "In this study, we demonstrate that DC‐exos are involved in endothelial inflammation through exosomal TNF‐α mediated NF‐κB pathway." (PMID 27515767, 2016). "AS-IV inhibited IL-1β, TNF-α, and nitric oxide (NO) and protected against IL-1β-induced joint inflammation and cartilage destruction in adjuvant-induced arthritis (AIA) rats." (PMID 27872860, 2016). "Firstly, we assessed levels of CAR phosphorylation in a murine model of TNFα-induced acute lung inflammation." (PMID 27193388, 2016). "TNF-α is an important cytokine involved in acute pleural inflammation leading to the development of parapneumonic effusion." (PMID 27034588, 2016). "In particular, ebselen reduces LPS-induced lung inflammation by reducing the levels of TNF-α and MIP-2, potent inducers of neutrophil activation." (PMID 26877172, 2016). "Consistent with worsened renal dysfunction, Ang II infusion in the ApoEKO mice exhibited exacerbation of kidney inflammation with enhanced expression of TNF-α, TNFRSF1A, IL-1β, IL-6, and IL-17A." (PMID 26245758, 2015). "Our previous studies indicated that oral ciclamilast is effective in the treatment of experimentally induced airway inflammation accompanied by reduction of TNF-α levels in lung tissues." (PMID 26000303, 2015). "IL-6, IL-1β, and TNF-α are all important cytokines that stimulate RASFs and inflammatory cells to aggravate synovial inflammation, resulting in joint destruction." (PMID 26303122, 2015). "The mechanism of this pharmacological potential of Boswellia serrata was investigated in colonic epithelial cell monolayers exposed to H2O2 or INF-γ+TNF-α, chosen as in vitro experimental model of intestinal inflammation." (PMID 25955295, 2015). "In acute lung injury, especially in LPS-induced lung inflammation, TNF-α plays a dominant role in LPS-induced mouse mortality." (PMID 25051011, 2014). "These animals develop spontaneous joint inflammation and cartilage destruction, but the administration of IL-33 inhibits the TNF-α-induced bone destruction via the IL-33/ST2 axis." (PMID 24692848, 2014). "Pancreatic inflammation in mice deficient in IFNAR1 ubiquitination was paralleled with an altered balance between pro-inflammatory and anti-inflammatory cytokines (e.g. TNFα and IL10) and increased expression of CCL2." (PMID 24480543, 2014). "Weaning induces transient gut inflammation in piglets and the expression levels of some pro-inflammatory cytokines such as IL-1β, IL-6 and TNF-α were up-regulated in newly weaned piglets." (PMID 24609095, 2014). "TNF-α was shown to be released along with histamine from rat brain MC, and was involved in brain inflammation." (PMID 25359293, 2014). "LPS-induced acute lung inflammation was significantly exacerbated in Spred-2−/− mice compared with WT mice, as indicated by the numbers of infiltrating leukocytes, levels of alveolar TNF-α, CXCL2 and CCL2 in a later phase, and lung pathology." (PMID 25275324, 2014). "It is well known that TNF-α is a key factor in the development of lung inflammation upon particle exposure." (PMID 25497724, 2014). "To assess lung inflammation, we performed total and differential cell counts and quantified levels of IL-1β, TNF-α, KC and MCP-1 by ELISA." (PMID 24495712, 2014). "In contrast to our findings, pulmonary inflammation as assessed by TNF-α, KC, IL-1β, and MIP-2 levels and histologic score is reduced in Nlrc4−/− mice infected with K. pneumoniae." (PMID 25232720, 2014).
inflammation (continued). "Pro-inflammatory cytokines, including several interleukins and tumor necrosis factor, are important mediators of the development of skin and mucosal inflammation." (PMID 25118798, 2014). "Cows with persistent uterine inflammation had higher serum concentrations of adiponectin, TNF-α, IL-1β and IL-6 compared to normal and recovered cows." (PMID 24209779, 2013). "In contrast, high dose IT IL-6 resulted in marked anti-inflammatory effects as judged by reduced BAL fluid cytokines (IL-6, CXCL1, TNF-α), lung inflammation (IL-6, CXCL1, IL-1β), and serum CXCL1." (PMID 23667439, 2013). "In a mouse model of airway inflammation, TNF-α and endothelial expression of TNF receptor 1 (TNF-R1) were increased, and inhibition of this pathway blocked remodeling." (PMID 23448258, 2013). "Cows with persistent postpartum uterine inflammation had higher serum concentrations of TNF-α, IL-6, leptin, but lower insulin and IGF-1 compared to normal and spontaneously recovered cows and there was a temporal association observed during the study period." (PMID 24209779, 2013). "Infiltrating leukocytes to areas of acute myocardial inflammation and post-MI myocardium are a source of inflammatory cytokines (e.g. IL-6, IL-1 and TNF-α) and contribute to local inflammation, remodelling and fibrosis of the myocardium." (PMID 23471223, 2013). "Treatment with 4% DSS for 6 days in our trial has caused a mild colonic inflammation as indicated by the distinct increase in the expression of pro-inflammatory parameters like COX2 and TNFα in group DSS compared to healthy Con rats." (PMID 23533793, 2013). "Using the LPS-AKI model, we found that administration of nicotinic agonists blunted kidney inflammation (e.g. TNFα, CCL2, and CXCL10)." (PMID 22586448, 2012). "Effector Tc1 cells, the classical cytotoxic T cells that produce IFN-γ and TNF-α, have been demonstrated to control lung inflammation during acute influenza virus infection." (PMID 22529945, 2012). "In conclusion, our study demonstrates for the first time that leukocyte ADAM17 regulates acute lung inflammation by modulating intra-alveolar neutrophil levels and the shedding of IL-6R, L-selectin, and TNF-α." (PMID 21603616, 2011). "MK-886 pretreatment attenuated subsequent pulmonary expression of TNF- α in a mouse model of bronchial inflammation and hyperreactivity." (PMID 21649921, 2011). "HIV-related chronic inflammation determines the expression of several cytokines especially in mononuclear cells such as IL-6, IL-8 and TNF α which activate endothelial cells and enhance leukocyte adhesion." (PMID 21612582, 2011). "Since neutrophilic pulmonary inflammation was enhanced in the lungs of Nrf2-/- mice at 1 and 3 days after bleomycin administration, the levels of TNF-α and MIP-2 were evaluated in the BAL fluid of both genotypes of mice at those time points." (PMID 20298567, 2010). "The IRP is, however, also characterized by an increase of pro-inflammatory cytokines (such as IL-6 and TNF-α) and a low grade, chronic inflammation." (PMID 20886083, 2010). "BCG induces a unique type of persisting bladder inflammation different from TNF-α, LPS, and, most likely other classical pro-inflammatory stimuli." (PMID 17506885, 2007). "In this context, a recent study using a mice model of acute lung inflammation shows that inflammatory recruited monocytes up-regulate gene expression of chemokines, TNFα and lysosomal proteases and down-regulate TLR-2 expression." (PMID 16606450, 2006). "Hypoxia stimulates reactive oxygen species (ROS) production and calcium release, activating inflammatory pathways (e.g., AP-1, STAT3, and MAPK) and increasing cytokines, such as IL-6, TNF-α, and IL-1, thereby exacerbating airway inflammation and lung ischemia–reperfusion injury." (PMID 41408473, 2025).
inflammation (continued). "Numerous studies have reported a positive correlation between HUA and inflammatory biomarkers, including CRP, TNF-α and N-methyl-D-aspartate, suggesting that uric acid may play a role in inflammation and subsequent inflammation-related diseases." (PMID 39980850, 2025). "Emerging data from early-phase human studies indicate that standardized herbal extracts can reduce chronic systemic inflammation (evidenced by decreases in IL-6 and TNF-α), correct energy dysmetabolism, and simultaneously suppress proteolysis while promoting myofibrillar protein synthesis." (PMID 41514616, 2025). "Furthermore, the transplantation of feces from patients with COPD into mice resulted in a notable elevation in IL-1 and TNF-α levels, accompanied by the induction of lung inflammation, compared to the control group." (PMID 41141595, 2025). "Studies have shown that persistent short sleep can induce low-grade systemic inflammation, increasing levels of C-reactive protein, IL-6, and TNF-α in the blood, thereby exacerbating chronic systemic inflammation, particularly in older and frail individuals, and promoting the onset of frailty." (PMID 41468459, 2025). "Chronic systemic inflammation, including C-reactive protein (CRP), interleukin-6 (IL-6), and tumor necrosis factor-alpha (TNF-α), has been associated with childhood maltreatment, and systemic inflammation has been identified as a gestational risk factor for adverse neurodevelopment in offspring." (PMID 40920854, 2025). "Escherichia-Shigella has been associated with NOD-like receptor protein 3 (NLRP3) inflammasome activation and elevated TNF-α production, contributing to renal inflammation, whereas Faecalibacterium and Bifidobacterium exert SCFA-mediated anti-inflammatory effects." (PMID 40978750, 2025). "The TNF and chemokine signaling pathways are particularly significant in synovial inflammation." (PMID 40699844, 2025). "The human TNF-α transgenic (hTNFtg) mouse model effectively replicated TMJ pathology seen in arthritic patients, including increased synovial inflammation (p=0.0024) and severe bone loss (p=0.009) as compared to control mice assessed by micro-computed tomography and histomorphometry." (PMID 40755771, 2025). "A similar effect was exhibited in this study; we found that PF significantly decreased the release of TNF-α and IL-1β in the serum of LPS-administrated rats and prevented cardiac inflammation, as illustrated by the reduction of TNF-α and IL-1β in cardiac tissue." (PMID 41311552, 2025). "These include the downregulation of natural anticoagulants present on the EC surface (TFPI, TM, and EPCR) mediated by TNF-α and IL-1β, as demonstrated in both acute and chronic inflammation, and variation of protein S and upregulation of endothelial adhesive molecule expression." (PMID 39877523, 2025). "Curcumin and its derivatives exert their effects by inhibiting the NF-κB signaling pathway, which downregulates pro-inflammatory factors such as COX-2, JNK, PI3K, and AP-1, thereby reducing the secretion of pro-inflammatory mediators like IL-6, IL-1β, TNF-α, and alleviating joint inflammation." (PMID 40806131, 2025). "Curcumin and resveratrol have demonstrated a synergistic ability to inhibit TNF-α-induced inflammation by suppressing the NF-κB signaling pathway, which is vital for reducing vascular inflammation and enhancing the function of mesenchymal stem cells (MSCs) in inflammatory conditions." (PMID 40699844, 2025). "Furthermore, omentin-1, an anti-inflammatory adipokine that inhibits TNF-induced vascular inflammation, exhibit low levels in patients with active CD and UC, emphasising the profound connection between IBD and adipose tissue." (PMID 40735319, 2025). "In the present study, S. aureus significantly elevated IL-1β expression (p < 0.05) and TNF-α expression of (p < 0.01) in the mammary gland, indicating the occurrence of mammary inflammation, while L. plantarum X86 inhibited the expression of these two cytokines to varying degrees." (PMID 40129572, 2025).
inflammation (continued). "Chronic intestinal inflammation in IBD is driven in part by elevated pro-inflammatory cytokines such as TNF-α, IL-6, IL-17, IL-1β, and IFN-γ, which collectively promote leukocyte recruitment, amplify epithelial injury, and sustain a feed-forward inflammatory loop." (PMID 41333470, 2025). "However, our group previously shown that MQEO had protective effect against intestinal inflammation in vivo and in vitro with potent anti-inflammatory properties via suppression of TNF-α and IL-1β." (PMID 38655301, 2024). "Systemic and pulmonary inflammation was measured by enzyme-linked immunosorbent assays of plasma and bronchoalveolar lavage (BAL), respectively, which included tumor necrosis factor alpha (TNF-α), interleukin 6 (IL-6), IL-10, C-X-C motif ligand 2 (CXCL2), and CXCL5." (PMID 38928327, 2024). "This study further analyzed the effect of CNDs on TNFα-induced endothelial inflammation." (PMID 38397822, 2024). "TNF-α is a significant pro-inflammatory cytokine that can trigger myocardial cell apoptosis signaling and exacerbate myocardial inflammatory necrosis in both acute and chronic cardiac inflammation." (PMID 39243097, 2024). "Decreased bone mass and bone density are caused by several factors involved in the pathogenesis of RA, such as the presence of pro-inflammatory cytokines (tumor necrosis factor-TNFα, Interleukin-1-IL-1, Interleukin-6-IL-6) and chronic systemic inflammation, which impacts bone metabolism." (PMID 38672734, 2024). "Additionally, ZDF diabetic animals showed pancreatic inflammation evidenced by increased levels of the inflammatory markers TNF-α, IL-6, and p-p65." (PMID 38257166, 2024). "In addition, the overexpression of pro-inflammatory cytokines, such as IL-6, TNF-α, and IL-1β, from the macrophages is further involved in the upregulation of inflammatory reactions resulting in inflammation-related diseases." (PMID 39200485, 2024). "Additionally, reports suggest that antitumor necrosis factor-α (anti-TNF-α) agents exhibit reduced efficacy in treating small intestinal inflammation compared to colorectal inflammation." (PMID 38864024, 2024). "Similarly, another study documented that saxagliptin and vildagliptin alleviated renal inflammation via attenuation of IL-1β, TNF-α as well as iNOS expression." (PMID 37615707, 2024). "TNF-α can damage the function of T cells by enhancing the dephosphorylation of Foxp3; and their function can be restored by TNF-α antagonist therapy, thereby indirectly regulating the interaction between T cells and Th17 and Th1 cells, which affects autoimmune inflammation in RA." (PMID 38807592, 2024). "Numerous studies have indicated that over-expressions of cytokines such as IL-1, IL-6, and TNF-α may promote liver inflammation during chronic liver injury." (PMID 38136147, 2023). "The authors concluded that up-regulated IL-33 levels may facilitate lung inflammation by promoting the production of a range of innate pro-inflammatory cytokines, including TNF-α, IL-1β, IL-6, IL-12, IL-23." (PMID 36875710, 2023). "Besides immune cells, Paneth cells also constitutively produce TNF-α in mice as well as in patients suffering from chronic intestinal inflammation." (PMID 36926182, 2023). "In addition to TNF-alpha, other pro-inflammatory cytokines also play a role in the development of pancreatic inflammation." (PMID 37175426, 2023). "Transwell co-cultures of Caco-2 cells and U937-derived macrophages were used as models of LPS-induced intestinal inflammation to test the effect of ME-3 on release of the pro-inflammatory cytokines Tumor Necrosis Factor α, Interleukin-6, and Interleukin-8, was measured by ELISA." (PMID 37047193, 2023). "Studies have shown that the expression of pro-inflammatory cytokines (such as IL-1β, IL-6, TNF-α, etc.)is significantly increased during intestinal inflammation, leading to a significant increase in intestinal epithelial tight-junction barrier permeability as a result of multiple effects." (PMID 37240380, 2023).